IL6 (interleukin 6)
Diseases named in the same sentence as IL6 in open-access papers (continued):
Sharing a sentence is not in itself a finding about the gene and the disease.
pulmonary fibrosis (continued). "Furthermore, IL-6 and TNF-α are strongly related to the development of lung fibrosis and EMT." (PMID 35463079, 2022). "Thus, by suppressing macrophages number and activity, and decreasing IL-6 levels, RSV-LNCs could effectively prevent progression of ARDS to irreversible pulmonary fibrosis." (PMID 35945895, 2022). "Here, we found that Fed inhibited IL-6- or TGF-β1-induced abnormal wound healing of epithelial cells and fibroblast-to-myofibroblast transition, reduced TGF-β1-induced myofibroblast activation and accumulation and, finally, alleviated bleomycin-induced mice pulmonary fibrosis and inflammation." (PMID 34361644, 2021). "Following bleomycin-induced lung injury, Il11−/− mice are protected from pulmonary fibrosis and exhibit lesser ERK, STAT3 and NF-kB activation, reduced Il1b, Timp1, Ccl2 and diminished IL6 expression, both at baseline and after injury: placing Il11 activity upstream of IL6 in this model." (PMID 34239012, 2021). "Furthermore, consistently unique cytokine expression patterns of regenerative and growth factors (CCL2, CCL11, IL6, IL12B, and CXCL8) may indicate activation of pulmonary fibrosis signaling pathways after aberrant inflammatory response." (PMID 35145507, 2021). "Western blot analysis of lung tissues in BLM-induced lung fibrosis mice showed an increased expression of extracellular matrix proteins, such as fibronectin, and phosphorylation of STAT3 (Tyr705) protein, a downstream mediator of IL-6 signaling, when compared with lung tissues of the control mice." (PMID 31049028, 2019). "Our previous studies demonstrate upregulation of multiple growth factors including TGFβ, IL-6, IL-13, amphiregulin and epiregulin in distinct mesenchymal cell subsets such as fibrocytes, lung resident fibroblasts and WT1-positive myofibroblasts during TGFα-induced pulmonary fibrosis." (PMID 31156440, 2019). "Downregulated expression of TNF-α, IL-1β, IL-6 and IL-10 proteins indicated that AD-MSCs can also protect the lungs from injury and fibrosis through an anti-inflammatory process, which was consistent with ample experimental evidence in MSC-treated pulmonary fibrosis." (PMID 29673394, 2018). "Again, IL-6 seems to have a dual role during BLM-induced lung injury: while it exerts an anti-fibrotic role during the early stage presumably by protecting IL-6 producing AECII in an autocrine/paracrine manner, IL-6 produced by macrophages and fibroblasts might promote pulmonary fibrosis." (PMID 28836991, 2017). "Surprisingly, pharmacologic inhibition of IL-6 by administration of a neutralizing antibody during the early phase increased apoptosis in AECII cells, neutrophil infiltration to the lung and fibrosis development, whereas IL-6 inhibition during the second phase ameliorated pulmonary fibrosis." (PMID 28836991, 2017). "In addition, bleomycin-induced lung fibrosis was significantly attenuated in mice lacking the IL-6 gene." (PMID 20302663, 2010). "Moreover, even after adjusting for IL6, VEGF, and CRP, ICAM1 + EVs remained an independent predictive factor of ILD progression, indicating that ICAM1 + EVs could be a crucial proinflammatory/profibrotic signal pathway in lung fibrosis." (PMID 40370719, 2025). "Of note, concerning systemic involvement in HOCl-SSc, iNOS−/−-MSC were not able to reduce fibrotic markers such as collagen 1 and α-SMA and inflammatory cytokines (IL-1β and IL-6) in lung tissue, while WT-MSC had a positive impact on pulmonary fibrosis in this model (data not shown)." (PMID 30622540, 2018). "We found that systemic supplementation with TGF-β1 ameliorated pulmonary fibrosis without increasing the number of Tregs, suggesting that SF-MSC-mediated Treg induction did not solely depend on the upregulation of systemic TGF-β1, but also depended on other factors such as strong IL-6 suppression." (PMID 34530920, 2021).
acute respiratory distress syndrome (407 papers, 2005 to 2026). Progressive and life-threatening pulmonary distress in the absence of an underlying pulmonary condition, usually following major trauma or surgery. "According to Liu and Hill, IL-6 plays a central role in the worsening of the inflammatory response and is strongly associated with the severity of symptoms, particularly in acute respiratory distress syndrome." (PMID 40397955, 2025). "A cytokine storm, characterized by increased levels of cytokines (e.g., IL‐6), can cause or worsen acute respiratory distress syndrome and multiorgan failure, which is a critical issue in COVID‐19." (PMID 39560399, 2024). "Increased IL-6 concentrations are also associated with increased mortality and duration of mechanical ventilation in patients with acute respiratory distress syndrome (ARDS) and AKI." (PMID 38966229, 2024). "IL-6 is increased in BALF of patients with acute respiratory distress syndrome, and high levels are associated with adverse events." (PMID 37119853, 2023). "Interleukin (IL)-6 has been considered as a potential pathogenic factor in the initiation of acute respiratory distress syndrome (ARDS)." (PMID 37228604, 2023). "IL-6 can be used as an early indicator of cytokine storms, which are directly associated with acute respiratory distress syndrome (ARDS) and mortality." (PMID 37896795, 2023). "Given that, high circulating IL-6 is linked with progress of acute respiratory distress syndrome (ARDS)." (PMID 35662743, 2022). "Dysregulated IL-6 production leads to levels 100–500 times higher than normal in patients experiencing hyperinflammation, as in severe acute respiratory distress syndrome (ARDS) associated with sepsis." (PMID 35928820, 2022). "In summary, LPS activated immune cytokines (IL-1B, IL6), induced the expression of HP, and further induced acute inflammatory response, and then caused the Acute respiratory distress syndrome." (PMID 34519633, 2021). "IL-6 is produced by diverse immune cells and implicated in development of acute respiratory distress syndrome (ARDS) and CRS." (PMID 34002026, 2021). "Inflammatory biomarkers, like IL-1B and IL-6, are associated with a worst outcome in patients with PH or adult respiratory distress syndrome." (PMID 30840669, 2019). "As for biomarkers associated with acute respiratory distress syndrome mortality, interleukin-1β, interleukin-6, interleukin-8, Kerbs von Lungren-6, and plasminogen activator inhibitor-1 were significantly increased in the lung fluid of patients who died." (PMID 30755248, 2019). "Increased serum IL-6 is linked to poor survival in patients with acute respiratory distress syndrome (ARDS)." (PMID 24379525, 2013). "IL-6 can be used as an early predictor of IgG responses and cytokine storms, which may cause fatal symptoms such as acute respiratory distress syndrome." (PMID 35248063, 2022). "Several studies have suggested that cytokine storms and acute respiratory distress syndrome are associated with high levels of proinflammatory cytokines, including very high levels of IL-6, that correlate with the severity of disease, especially in patients with a high plasma viral load." (PMID 33467724, 2021). "Other hyperinflammatory conditions in the lung such as acute respiratory distress syndrome (ARDS) and coronavirus disease‐2019 (COVID‐19) are also often associated with elevated IL‐6 production." (PMID 41099307, 2026). "IL-6, another cytokine implicated in lung diseases such as sub-acute respiratory distress syndrome (ARDS), plays a role in Th17 cell differentiation and the sub-acute phase response, which can worsen respiratory conditions." (PMID 40594334, 2025). "Interleukin (IL)-6 was identified as one of the first potentially pathogenic factors in the development of acute respiratory distress syndrome (ARDS) in the course of COVID-19." (PMID 36810662, 2023).
acute respiratory distress syndrome (continued). "Cytokine release syndrome, characterized by increased levels of cytokines (such as IL-6), can cause or worsen acute respiratory distress syndrome (ARDS) and multiple organ failure." (PMID 36945235, 2023). "Both IL-6 and IL-1-ß increase endothelial permeability thereby causing acute respiratory distress syndrome (ARDS) in COVID-19 patients." (PMID 36579259, 2022). "The cytokine storm, including an overproduction of interleukin-6 (IL-6), is thought to cause acute respiratory distress syndrome (ARDS)." (PMID 35529699, 2022). "High levels of IL-1β, IL-6, IP-10, and TNFα have been associated with acute respiratory distress syndrome (ARDS), severe disease, and mortality following SARS-CoV-2 infection." (PMID 36865568, 2022). "Increased IL-6 expression is a hallmark of COVID-19 in association with acute respiratory distress syndrome (ARDS) and respiratory failure." (PMID 34790202, 2021). "Among the numerous cytokines that are released, interleukin-6 (IL-6) is thought to play a major role in causing acute respiratory distress syndrome (ARDS)." (PMID 33353546, 2020). "Severe cases result in acute respiratory distress syndrome (ARDS) with systemic inflammation in which lung injury is associated with release of inflammatory cytokines IL-6 and IL-1β." (PMID 32655582, 2020). "High levels of IL-6, IL-8, sTNFR1, and Ang-2 in plasma samples of patients with the acute respiratory distress syndrome (ARDS) are well-known for their association with poor outcomes." (PMID 32955627, 2020). "The viral entry initiates a cascade of events that includes the infiltration of proinflammatory markers, such as interleukin-2, interleukin-6, and tumor necrosis factor-alpha, leading to the development of acute respiratory distress syndrome." (PMID 40621321, 2025). "This cascade culminates in a CS characterized by excessive IL-6, IL-1β, TNF-α, and IFNs, amplifying lung inflammation and increasing susceptibility to acute respiratory distress syndrome (ARDS)​." (PMID 40330025, 2025). "Elevated IL-6 levels drive systemic inflammation, leading to acute respiratory distress syndrome (ARDS), coagulopathies, and multi-organ failure." (PMID 39599491, 2024). "Seven cytokines showed a significant positive correlation with disease severity (|Rho| > 0.2, partial Spearman correlation), including proinflammatory T helper 1 (TH1)-related cytokines (IP-10, MIP-1a) and acute respiratory distress syndrome (ARDS)-associated cytokines (IL-6, IL-8, IL-1ra, MCP-1)." (PMID 38779486, 2024). "IL-6, in particular, has been suggested as a potential therapeutic target for acute respiratory distress syndrome (ARDS) in SARS-CoV-2-infected COVID-19 patients." (PMID 37513775, 2023). "Increased IL-6 level after LPS exposure is usually occur and followed by different pathological conditions such as lung injuries leading to acute respiratory distress syndrome." (PMID 36773191, 2023). "A pilot clinical trial of recombinant human ACE2 in acute respiratory distress syndrome demonstrated that ACE2 decreased IL-6 concentrations, suggesting an anti-inflammatory effect of ACE226." (PMID 37221286, 2023). "IL-6 plays a role in the genesis of the pro-inflammatory lung-systemic loop leading to a cytokine storm syndrome and acute respiratory distress syndrome." (PMID 37752433, 2023). "Tocilizumab, classified among IL-6 inhibitors, is recognized for its potential in managing acute respiratory distress syndrome (ARDS) induced by cytokine storms in affected patients." (PMID 37986199, 2023). "In addition, high serum IL‐6 levels are significantly associated with adverse clinical outcomes, including acute respiratory distress syndrome (ARDS), invasive mechanical ventilation, ICU admission, and death." (PMID 36759335, 2023). "Immune activation and CRS were evidenced by a rapid increase in serum cytokines (IL-6, TNFα, IL-8, IL-10), acute respiratory insufficiency, and progressive acute respiratory distress syndrome." (PMID 35692034, 2022).
acute respiratory distress syndrome (continued). "In particular, IL-6 and TNF-α are the two key cytokines involved in the development of the cytokine storm underlying acute respiratory distress syndrome (ARDS), which can be down-regulated by VD." (PMID 36615826, 2022). "As known the most serious cases develop an acute respiratory distress syndrome (ARDS) characterized by high levels of pro-inflammatory cytokines especially IL-6." (PMID 35268625, 2022). "In acute respiratory distress syndrome, NETs aggravate alveolar macrophage pyroptosis, and ASC foci, caspase-1, IL-1β, IL-6, and TNF-α are significantly associated with elevated NETs." (PMID 36430491, 2022). "TNF, IL-1, IL-6, and IL-8 have been shown to be elevated in individuals with acute respiratory distress syndrome and septic shock." (PMID 35450105, 2022). "In CRS, infusion of cytotoxic T-cells leads to a rampant release of cytokines like IFN-γ, GM-CSF, TNF, IL-10, and IL-6, triggering an inflammatory response characterized by tachycardia, risk for acute respiratory distress syndrome (ARDS) acute hypoxic respiratory failure, and multiorgan failure." (PMID 34512641, 2021). "It is assumed that chloroquine inhibits the production of proinflammatory cytokines (such as interleukin-6) by reducing acute respiratory distress syndrome (ARDS)." (PMID 33898518, 2021). "Within the lung, IL-6 promotes lung inflammation, and IL-6 levels are related to the severity of acute respiratory distress syndrome as well as mortality." (PMID 34692664, 2021). "In contrast, median IL‐6 after 7 days of admission (231.4 vs 534.6 pg/ml, P = .433) and the incidence of acute respiratory distress syndrome (ARDS) (19.6% vs 27.1%, P = .06) were lower in transplant recipients than in the control group." (PMID 34155789, 2021). "There is some evidence that with extracorporeal cytokine adsorption, substantial IL-6 removal is achievable in severely ill patients with septic shock, acute respiratory distress syndrome (ARDS), and multi-organ failure." (PMID 34869464, 2021). "Studies carried out on IL-6−/− mice suffering from acute respiratory distress syndrome (ARDS) showed that the spread of SARS-CoV was more in IL-6−/− mice as compared to the control (IL-6+ mice)." (PMID 33815095, 2020). "Recombinant human ACE2 (APN01), developed in 2010, has been demonstrated to be able to reduce levels of both Ang2 and IL-6 in a phase II study of acute respiratory distress syndrome." (PMID 33193019, 2020). "Interleukin-6 (IL-6) seems to have a pivotal role in the production of diffuse alveolar damage and acute respiratory distress syndrome." (PMID 33304913, 2020). "IL-6 has been shown to provide prognostic value in acute respiratory distress syndrome (ARDS), which is the most severe form of COVID-19 disease." (PMID 32574262, 2020). "In severe cases the disease progresses into an Acute Respiratory Distress Syndrome (ARDS), which in turn depends on an overproduction of cytokines (IL-6, TNFα, IL-12, IL-8, CCL-2 and IL1) that causes alveolar and vascular lung damage." (PMID 32922210, 2020). "Interleukin 6 (IL-6) is a predictive factor of poor prognosis in patients with acute respiratory distress syndrome (ARDS)." (PMID 28424078, 2017). "Several reports confirmed that high levels of IL-6 and TNF-α are associated with acute respiratory distress syndrome and acute lung injury." (PMID 25337912, 2014). "Pro-inflammatory interleukins like IL-1β, IL-6, IL-2, IL-17 and IL-18 are critically involved in cytokine storm, hyperinflammation, and acute respiratory distress syndrome, whereas anti-inflammatory cytokines like IL-10 contribute to immune regulation and resolution of inflammation." (PMID 41683812, 2026). "Prospective cohorts have subsequently confirmed that early IL-6 levels predict progression to acute respiratory distress syndrome (ARDS), need for mechanical ventilation, and prolonged hospitalisation, supporting its use for risk stratification and dynamic monitoring." (PMID 41517263, 2025).
acute respiratory distress syndrome (continued). "The cytokine storm phenomenon is an increase in pro-inflammatory cytokine levels in the serum, such as IL-2, IL-6 and IL-1β, IL-17, IL-8, G-CSF, GM-CSF, IP10, MCP1, MIP1α (also known as CCL3), and TNF, and causes acute respiratory distress syndrome (ARDS) in severe COVID-19 cases." (PMID 37626992, 2023). "One of the major complications of SARS-COV-2 is the acute respiratory distress syndrome (ARDS), which could be caused by the excessive production of pro-inflammatory cytokines (cytokine storm syndromes) such as interleukin (IL)-6." (PMID 37895148, 2023). "CRS may trigger the release of interleukin-6 (IL-6), which plays a major role in acute respiratory distress syndrome (ARDS) and is correlated with poor clinical outcomes." (PMID 37384095, 2023). "IL-6 signaling was shown to play a crucial role in vascular endothelial cell dysfunction in cytokine release syndrome and the progression of acute inflammatory diseases such as acute respiratory distress syndrome." (PMID 35107382, 2022). "IL-6 is an important driver of the inflammatory cytokine storm, which might lead to acute lung injury, acute respiratory distress syndrome, and other tissue damages, progressing to multiple organ failure." (PMID 34712742, 2021). "Indeed, increased TNF-α, IL-1β, and IL-6 levels were detected in the BALF of patients with acute respiratory distress syndrome." (PMID 34745417, 2021). "The COVID-19 infection has also been observed to induce pro-inflammatory cytokine generation and secretion of cytokines, such as IL-6, which dysregulates the local inflammatory responses that have been suggested as partially responsible for the devastating acute respiratory distress syndrome." (PMID 32256705, 2020). "In these patients, cytokine release may play a significant role in the development of acute respiratory distress syndrome, raising the hypothesis that interleukin-6 inhibitors such as tocilizumab may be of benefit." (PMID 33318918, 2020). "Patients that died had elevated IL-6 levels and acute respiratory distress syndrome." (PMID 32406037, 2020). "Exuberant host responses, i.e., a cytokine storm with increase of macrophage-related cytokines, such as TNFα, IL-1β, and IL-6 can lead to life-threatening complications, such as acute respiratory distress syndrome (ARDS), which develops in approximately 20% of the patients." (PMID 32916949, 2020). "Elevated levels of pro-inflammatory cytokines and chemokines (e.g., TNFα, IFNγ, IL-1, IL-6, IL-8, IL-9, IL-12 IL-15, and IL-17) have been found, up to 10 days after the onset of symptoms, in the plasma of patients with acute respiratory distress syndrome (ARDS) caused by influenza A/H1N1." (PMID 32219005, 2019). "Lung fibroblasts exposed to lung edema fluid from patients with early stage acute respiratory distress syndrome (ARDS) produce increased amounts of IL-6, which in turn stimulates fibroblast activation and proliferation in an autocrine manner via gp130 signaling." (PMID 28139758, 2017). "Previous studies have demonstrated that highly elevated IL-6, IL-1, TNF-α, IFN-γ, MIP, CXCL10 are major causes of ARDS (acute respiratory distress syndrome) and mortality, and TGF-β1 could restrict inflammatory response." (PMID 25909459, 2015). "IL-6 release seems to play a key role in acute respiratory distress syndrome (ARDS), although its detailed mechanism of action remains unclear." (PMID 25265888, 2014). "Elevated levels of pro-inflammatory cytokines and chemokines (e.g., TNFα, IFNγ, IL-1, IL-6, IL-8, IL-9, IL-12 IL-15, and IL-17) have been found, up to ten days after the onset of symptoms, in the plasma of patients with acute respiratory distress syndrome (ARDS) caused by influenza A/H1N1." (PMID 23148654, 2012).